TOP2A (DNA topoisomerase II alpha)
Diseases named in the same sentence as TOP2A in open-access papers (continued):
Sharing a sentence is not in itself a finding about the gene and the disease.
hepatocellular carcinoma (continued). "RACGAP1, TOP2A and some other genes co-expressed to regulate the immunity response in hepatocellular carcinoma." (PMID 33193623, 2020). "TOP2A overexpression in hepatocellular carcinoma correlates with early age onset, shorter patient survival, and chemoresistance." (PMID 32368301, 2020). "TOP2A may promote hepatocellular carcinoma progression by facilitating epithelial‐mesenchymal transition mediated by the p‐ERK1/2/p‐SMAD2/Snail pathway, which has been associated with a poor prognosis in hepatocellular carcinoma." (PMID 38661103, 2024). "In addition, our data suggest that overexpression of miR-144-3p can resist the process that TOP2A promotes the proliferation, migration invasion of hepatocellular carcinoma cells." (PMID 35069905, 2022). "TOP2A may be a new biomarker and therapeutic target for hepatocellular carcinoma." (PMID 35033076, 2022). "Thus, our results indicated that curcumin might decrease the expression of AURKA, CDK1 and TOP2A to reverse chemoresistance in hepatocellular carcinoma treatment." (PMID 35078445, 2022). "Type IIA topoisomerase (TOP2A) is upregulated in hepatocellular carcinoma (HCC) and its expression is positively correlated with poor prognosis." (PMID 34939898, 2021). "Future research should aim to increase the sample size to validate these results and further investigate the functional roles of TOP2A and HMGB2 in the pathogenesis and treatment resistance of hepatocellular carcinoma (HB)." (PMID 40099956, 2025). "AP-2α directly regulates transcription of critical DNA repair genes such as TOP2A, NUDT1, POLD1, and PARP1 in hepatocellular carcinoma, thereby facilitating repair of oxidized DNA lesions." (PMID 41373739, 2025). "Several studies have reported significant upregulation of TOP2A mRNA and protein expression in hepatocellular carcinoma (HCC), suggesting that TOP2A is overexpressed in this cancer type and may serve as a potential biomarker for HCC." (PMID 38144520, 2023). "Our results provided a novel panel of AURKA, CDK1, TOP2A, CYP2C9, and CYP3A4 candidate genes for curcumin related chemotherapy of hepatocellular carcinoma." (PMID 35078445, 2022). "Overexpression of miR-144-3p resisted the process that TOP2A promoted the proliferation, migration, invasion and EMT of hepatocellular carcinoma cells." (PMID 35069905, 2022). "Whether TOP2A plays an important role in hepatocellular carcinoma (HCC) remains unclear." (PMID 35069905, 2022). "When we merged these hub genes with differentially expressed genes in GSE14520 dataset and differentially expressed genes of hepatocellular carcinoma in GEPIA database, seven communal genes were found, they were AURKA, CDK1, CCNB1, TOP2A, CYP3A4, CYP2C9, and CYP2B6." (PMID 35078445, 2022). "In summary, so far as we known, our results first showed that CDK1, TOP2A, CYP2C9, and CYP3A4 genes correlated to curcumin-related chemotherapy of hepatocellular carcinoma, more than just correlated to diagnosis and prognosis of hepatocellular carcinoma which had highlighted by the previous studies." (PMID 35078445, 2022). "However, our only high evidence study (level ID) on hepatocellular carcinoma patients showed no benefit of TOP2A overexpression on anthracycline based therapies." (PMID 27888622, 2017).
pancreatic cancer (38 papers, 2019 to 2025). "TOP2A (topoisomerase IIα) is overexpressed in pancreatic cancer and linked to worse survival outcomes." (PMID 41008826, 2025). "TOP2A is upregulated in pancreatic cancer, and its upregulation is associated with tumor metastasis and shorter survival." (PMID 38008711, 2023). "ASPM, CCNB1, CDK1, MELK, OAS3, PPTG1 and TOP2A were thought to be significantly associated with shorter overall survival in pancreatic cancer patients." (PMID 36167975, 2022). "High expression of TOP2A was significantly associated with tumor metastasis and shorter survival in pancreatic cancer patients, and knockdown of TOP2A inhibited proliferation and migration in Panc-1 and CaPan-1 cell lines." (PMID 32537471, 2020). "TOP2A has been shown in pancreatic cancer cell lines to be associated with proliferation and migration through activation of the β-catenin signalling pathway." (PMID 32024004, 2020). "Studies have confirmed that TOP2A is implicated in various types of tumors, such as gastric cancer, colon cancer, pancreatic cancer (Pei, Yin & Liu, 2018) and papillary renal cell carcinoma." (PMID 31788359, 2019). "TOP2A expression is upregulated in pancreatic cancer tissues compared to non-tumor tissues, and its upregulation is significantly associated with tumor metastasis and shorter survival in pancreatic cancer patients." (PMID 38144520, 2023). "Utilizing XGBoost and RF, we pinpointed 10 genes closely related to pancreatic cancer, culminating in the identification of RAP1GDS1, TOP2A, ADK, POLL, CD44, and CD4 as pivotal genes linked to hypoxia in pancreatitis." (PMID 40787634, 2025). "In vivo and in vitro studies in pancreatic cancer have shown that short hairpin RNA (shRNA)-mediated TOP2A knockdown significantly reduces cell proliferation and migration and decreases tumor size in mouse models." (PMID 40732340, 2025). "By activating the Wnt/β-catenin pathway, TOP2A accelerates pancreatic tumor proliferation and migration." (PMID 41008826, 2025). "COL5A1 was detected to be highly expressed in multiple cancers, including breast, ovarian and pancreatic cancer; Topoisomerase II alpha (TOP2A) is necessary for the cell cycle and highly expressed during the mitotic process." (PMID 39063036, 2024). "In the mRNA expression profiles analysed using the GEPIA Platform, PRRX1 and TOP2A were highly expressed in glioblastoma and pancreatic cancer as well as MPNST." (PMID 38448751, 2024). "Among these, PLK1, SPC24, KIF2C, TOP2A, MKI67, and KIF4A, have been implicated in cancer development and serve as important biomarkers of proliferative activity in pancreatic cancer." (PMID 38250721, 2024). "Some studies on pancreatic cancer have shown that TOP2A modulates its biological behavior by activating the canonical Wnt signaling pathway and acting as a co-activator of β-catenin to stimulate actin transduction." (PMID 38806610, 2024). "Further analysis using the public database GEPIA revealed that the expression of six genes (PLK1, SPC24, KIF2C, TOP2A, MKI67, and KIF4A) was significantly associated with overall survival in pancreatic cancer patients." (PMID 38250721, 2024). "The clinical and prognostic values of TOP2A in breast carcinoma, nasopharyngeal carcinoma, and pancreatic cancer have also been sufficiently validated." (PMID 35012441, 2022). "High expression of TOP2A had effects on poor prognosis and enhanced metastasis capabilities of in pancreatic cancers." (PMID 35069905, 2022). "A previous study proved that TOP2A accelerated the development of pancreatic cancer through the activation of the β-catenin pathway." (PMID 36003146, 2022). "Except for IGFBP3 which hadn’t been found in HPA, as we predicted, protein expressions of PTGS2 (p < 0.01) and TOP2A (p < 0.001) were higher in pancreatic tumor tissue, which was consistent with their correlation with poor survival of PAAD patients." (PMID 36003146, 2022).
pancreatic cancer (continued). "Inhibition TOP2A results in alterations of signaling and the following pathways: overexpression of TOP2A actives β-catenin pathway in pancreatic cancer 12; downregulation of TOP2A inhibits the activity of EPK and AKT in colon cancer." (PMID 32201520, 2020). "TOP2A has been shown to be a prognostic indicator for inhibiting the proliferation and invasion of pancreatic cancer and bladder cancer." (PMID 32201520, 2020). "Previous studies have provided evidence about the expression of CDK1 and TOP2A in pancreatic cancer, but the correlation between them in pancreatic cancer has not been fully elucidated." (PMID 32587798, 2020). "The function and mechanism of TOP2A in pancreatic cancer have been fully verified." (PMID 38806610, 2024). "Knockdown of TOP2A in pancreatic cancer cell lines inhibits cell proliferation and migration." (PMID 38144520, 2023). "Down-regulating PLAU or TOP2A can inhibit pancreatic cancer cell proliferation and migration." (PMID 36741321, 2023). "In pancreatic cancer, the Wnt/β-catenin signaling pathway is activated by high TOP2A expression." (PMID 35912241, 2022). "In pancreatic cancer, TOP2A was found to promote malignancy via activating β-catenin." (PMID 35012441, 2022). "Inhibition of TOP2A expression results in altered signaling: in the context of pancreatic cancer, TOP2A overexpression activates the β-catenin pathway, while TOP2A downregulation inhibits extracellular signal-regulated kinase (ERK) and AKT activity in colon cancer." (PMID 34939898, 2021). "We also investigated if the cisplatin sensitivity of pancreatic cancer cells could be increased by TOP2A knockdown." (PMID 32977589, 2020). "Similarly, DGCR5 was proved that can promote pancreatic cancer by targeting miR-3163/TOP2A." (PMID 36003146, 2022). "Furthermore, CDK1 might phosphorylate TOP2A to promote S phase transition and influence the progression of pancreatic cancer, but follow-up research is needed to determine the specific mechanism of the interaction." (PMID 32587798, 2020). "In addition, TOP2A downregulation was found to inhibit the proliferation and migration or invasion of pancreatic and colon cancer cell lines and involved the β-catenin signaling pathway in pancreatic cancer." (PMID 31105744, 2019). "TOP2A and CDK1 are cell cycle-related genes and they facilitate proliferation and invasion of pancreatic cancer." (PMID 33748143, 2021). "In the development and progression of pancreatic cancer, miR-30 c had vital functions by targeting twinfilin 1 (TWF1) or DNA topoisomerase II alpha gene (TOP2A)." (PMID 34503377, 2021). "Therefore, we analysed protein levels in MPNST, glioblastoma, pancreatic cancer and small cell lung cancer cell lines and confirmed the expression of PRRX1 and TOP2A." (PMID 38448751, 2024). "TOP2A activates β-catenin pathway and EMT process in pancreatic cancer." (PMID 36741321, 2023). "Based on the transcriptomics profiling of anlotinib in this work and available pancreatic cancer related data deposited in TCGA, GEO, and ICGC databases, we further constructed a prognostic model which consists of five crucial genes, namely TOP2A, CRABP2, CDK1, NUSAP1, and PERP." (PMID 33748143, 2021). "The analytic results demonstrated that 7 upregulated (MMP9, CXCL8, ACTB, ITGB1, STAT1, TOP2A and CDK1) and 2 downregulated (GNMT and ABAT) hub genes may act as the key genes in pancreatic cancer." (PMID 31061236, 2019).
colon cancer (30 papers, 2014 to 2024). "As a risk factor for NRS score, TOP2A has also been reported to be associated with poor prognosis in pancreatic and colon cancers." (PMID 35422802, 2022). "Studies have shown that TOP2A played important roles in the tumorigenesis of many types of cancer, including colon cancer, and knockdown of TOP2A suppressed the proliferation and invasion of colon cancer cells." (PMID 35610288, 2022). "For example, TOP2A was identified as a potential biomarker for cancer therapy in ovarian cancer, colon cancer, pancreatic adenocarcinoma, and HCC." (PMID 33712023, 2021). "TOP2A is an oncogene for colon cancer, and even after development, TOP2A is over-expressed in the cancer cells." (PMID 34907282, 2021). "Binding of CBX4 to the promoter of TOP2α was confirmed by chromatin immunoprecipitation (ChIP) coupled with qPCR in LoVo colon cancer cells." (PMID 32358485, 2020). "Meanwhile, decreased expression of TOP2A inhibited the proliferation of invasion of colon cancer cells." (PMID 30671382, 2018). "TOP2A expression was upregulated in colon cancer than non‐cancer, and knockdown of TOP2A could inhibit cancer cell growth and invasion." (PMID 33527765, 2021). "Overall, our high-throughput drug panel established that RAMS11 expression impacted cellular sensitivity to topoisomerase inhibitors, specifically inhibitors targeting TOP2α, which led to the discovery that RAMS11 overexpression increased TOP2α protein expression in colon cancer cell lines." (PMID 32358485, 2020). "Several studies have shown that TOP2A induces the progression of many cancers, such as HCC, breast, prostate, lung and colon cancer." (PMID 34939898, 2021). "Some researchers reported that TOP2A could induce apoptosis and suppress cell growth and invasion via AKT/ERK signaling pathways in colon cancer." (PMID 34384030, 2021). "Similarly, five genes including TOP2A, REL, SHH, ROS1, and CHEK2 in colon cancer gene network and three genes including RBL1, MAPK9, and PIK3CA in adenocarcinoma of lung gene network are selected." (PMID 29670664, 2018).
glioblastoma (29 papers, 2013 to 2025). The most malignant astrocytic tumor (WHO grade IV). "TOP2A inhibitors combined with the neddylation inhibitor MLN4924 show a synergistic effect in glioblastoma." (PMID 38008711, 2023). "And, TOP2A was reported to be targeted by tumor suppressor like miR-144-3p in glioblastoma, thus resulting in cancer cell apoptosis." (PMID 31528121, 2019). "Our data show that silencing TRAF3IP2 down regulates TOP2A expression by a significant ∼7.5-fold in the malignant U87 glioblastoma cell line." (PMID 30038719, 2018). "Our findings suggest that AKBA can arrest cell cycling at the G2/M point by regulating the p21/FOXM1/cyclin B1 pathway and that AKBA can inhibit mitosis of glioblastoma cells by down-regulating the Aurora B/ TOP2A pathway." (PMID 29970196, 2018). "Using RNA-sequencing and western blotting analyses, we also found that AKBA arrested the cell cycle at the G2/M phase by regulating the p21/FOXM1/cyclin B1 pathway and inhibited mitosis of glioblastoma cells by downregulating the Aurora B/TOP2A pathway." (PMID 29970196, 2018). "TOP2A (Topoisomerase 2A) was found to be upregulated in glioblastoma compared to the lower grades and the mRNA levels of TOP2A correlated with the better survival in glioblastoma patients." (PMID 24475040, 2014). "Elevated expression of TOP2A was detected in glioblastoma cancer stem cells (CSCs) and silencing it led to reduced cell proliferation, cell cycle arrest, and increased apoptosis in glioblastoma CSCs." (PMID 38971772, 2024). "Though bioinformatic analyses suggest that TOP2A may be associated with ferroptosis, further studies are needed to figure out the whole gene regulation network that contains MKI67 and TOP2A in glioblastoma ferroptosis." (PMID 37834393, 2023). "The analysis reveals that GINS1 promotes glioblastoma cell proliferation and migration through the mediation of USP15 and TOP2A deubiquitination." (PMID 38301047, 2024). "TOP1/TOP2A and PARP poisons are already an important component of many treatment protocols for glioblastoma, sarcoma and other ALT + tumour types." (PMID 36940725, 2023). "TOP2A, COL4A1 and PXDN were significantly upregulated and ANK3, ARRB1 and ANO4 markedly downregulated in glioblastoma compared to controls." (PMID 32962742, 2020). "ST1926 similarly reduced TOP2A and POLA2 in glioblastoma cell lines." (PMID 40429796, 2025). "The data are consistent with a mechanism in which AKBA arrested the cell cycle in glioblastoma cells at the G2/M phase by regulating the p21/FOXM1/cyclin B1 pathway, inhibited mitosis by downregulating the Aurora B/TOP2A pathway, and induced mitochondrial-dependent apoptosis." (PMID 29970196, 2018). "It is not clear whether the downregulation of MKI67 and TOP2A are just induced by increased oxidative stress in ferroptotic glioblastoma cells or whether these two genes also take part in the regulation of ferroptosis." (PMID 37834393, 2023).